STAT3 (signal transducer and activator of transcription 3)
Diseases named in the same sentence as STAT3 in open-access papers (continued):
Sharing a sentence is not in itself a finding about the gene and the disease.
hepatocellular carcinoma (continued). "Blockade of IL-6-induced STAT3 in hepatocellular carcinoma cell lines facilitates doxorubicin-mediated apoptosis in previously doxorubicin-resistant cells." (PMID 28186993, 2017). "In summary, this study reports that oncogenic miR-500a-3p promotes the CSCs properties and tumourigenicity by negatively regulating SOCS2, SOCS4 and PTPN11, leading to activation of the STAT3 signalling pathway in hepatocellular carcinoma." (PMID 28750679, 2017). "Physical interactions between NF-κB family members, especially p65 with STAT3 have been reported in human mesangial cells and hepatocellular carcinoma cell lines." (PMID 28955792, 2017). "STAT3 is overexpressed in more than 90% of human carcinomas, including the breast, lung, colorectal, and hepatoma." (PMID 29115974, 2017). "Accordingly, the expression of phosphorylated STAT3 (active STAT3) was decreased in dysplastic nodules compared with chronic hepatitis tissues and completely lost in hepatocellular carcinoma tissue, which is similar to the pattern of SHP2 expression." (PMID 28460481, 2017). "This STAT-3/Twist1 axis has also been verified in hepatocellular carcinoma cells and the Notch1/STAT3/Twist1 signaling axis has been identified in gastric cancer." (PMID 28099910, 2017). "In hepatoma cells, IL-6-induced signal transducer and activator of transcription 3 (STAT3) activation facilitates viral gene transcription and is required for HCC formation and growth." (PMID 27434097, 2016). "Here, we have shown a specific role for the lipid species, ceramide in the regulation of HAMP transcription via the activation of JAK/STAT3 signaling in human hepatoma cells." (PMID 26807955, 2016). "CD44s also upregulates stem cell self-renewal genes Nanog, Sox-2, and Rex-1 and signal transducer and activator of transcription 3 (STAT3) in hepatocellular carcinoma cells." (PMID 27107424, 2016). "When STAT3 expression levels were reduced in a hepatocellular carcinoma (HCC) cell line using siRNA, hTERT expression was consequently reduced." (PMID 27548225, 2016). "We searched the available articles reporting the prognostic value of p-STAT3 in patients with cancers of the digestive system, mainly including colorectal cancer, gastric cancer, hepatocellular carcinoma, esophagus cancer and pancreatic cancer." (PMID 26024373, 2015). "We have previously demonstrated that PTPRO represses development of hepatocellular carcinoma by down-regulation of STAT3 (signal transducers and activators of transcription 3)." (PMID 25826083, 2015). "We delineate Oct4 and Nanog initiate stem cell characteristics in hepatocellular carcinoma and promote epithelial-mesenchymal transition through activation of Stat3/Snail signaling." (PMID 25879771, 2015). "To further understand the sequential events induced by ConA-stimulated hepatoma cells, we used Stattic (STAT3 activation inhibitor) and found that it suppressed STAT3 phosphorylation, BNIP3 induction and LC3-II conversion." (PMID 26633714, 2015). "The constitutive activation of STAT3 is frequently detected in clinical samples from a wide range of human carcinoma such as multiple myeloma, glioblastoma, colorectal and hepatocellular carcinoma." (PMID 26417930, 2015). "Amongst these pathways, only Ser727-phosphorylated STAT3 was activated in HSC-CM-treated hepatoma cells." (PMID 26593962, 2015). "Taken together, these results demonstrated that a-HSCs partially exerted their angiogenic function via IL-8, which up-regulated Ser727-phosphorylated STAT3 levels in hepatoma cells." (PMID 26593962, 2015). "Direct crosstalk between Smad3 and STAT3 was reported as the augmentation of IL-6-STAT3-mediated transactivation by TGF-β via interaction of the STAT3–pSmad3C complex bridged by p300 in hepatoma cells." (PMID 26194464, 2015). "Blocking the STAT3 activity is in favor of reversing the hepatocellular carcinoma-induced immune suppression and enhancing the NK cell functions." (PMID 26631279, 2015).
hepatocellular carcinoma (continued). "The IL-6/STAT3 signaling pathway also plays important roles in promoting the progression of hepatocellular carcinoma (HCC) by TAMs." (PMID 26016502, 2015). "Astaxanthin was shown to inhibit rat hepatocellular carcinoma CBRH-7919 cells by modulating the JAK/STAT-3 signaling." (PMID 25296162, 2014). "We found that in two out of the three examined hepatoma cell lines, STAT3 expression and STAT3 phosphorylation as markers for immune responses were strongly reduced following pK1-5 treatment." (PMID 24895598, 2014). "IL-6 induced expression of CDC25A in a STAT3-dependent manner in human hepatocellular carcinoma cells." (PMID 24743777, 2014). "There have been few reports showing the role of STAT3 in anoikis in squamous cell carcinoma and hepatocellular carcinoma." (PMID 25216522, 2014). "Like in PCa, VEGF expression is important for hepatocellular carcinoma progression, which is often associated with hepatitis C viral infection, and HCV infection induces STAT3 and AR dependent VEGF expression." (PMID 24722453, 2014). "STAT3 plays a critical role in mediating the antitumor effect of sorafenib on hepatocellular carcinoma." (PMID 25333973, 2014). "STAT3 has been shown to directly target the TIMP-1 gene as IL-6 has been observed to up regulate TIMP-1 levels in a STAT3-dependent manner in human hepatocellular carcinoma cells as well as human fibroblasts." (PMID 24743777, 2014). "STAT3 was found to bind to predicted STAT binding sequences within the JUNB promoter in response to IL-6 treatment in HepG2 hepatocellular carcinoma cells." (PMID 24743777, 2014). "Expression of STAT3 induced transcriptional activation of the SAA1 and SAA2 genes in HepG2 hepatocellular carcinoma cells whereas a STAT3 dominant negative suppressed their activation." (PMID 24743777, 2014). "In mouse models of hepatocellular carcinoma, miR-124 is involved in an inflammatory feedback loop where it suppresses the expression of IL-6R and reduces STAT3 activation in transformed cells." (PMID 23940556, 2013). "On the contrary, an inverse relationship between NF-κB and STAT3 was also shown in human hepatocellular carcinoma cells, in which IKKβ deletion increased STAT3 activation, tumorigenesis and tumor growth." (PMID 23402362, 2013). "IL-22 has been shown to support the growth of mantle cell lymphoma, anaplastic large cell lymphoma, hepatocellular carcinoma and colon carcinoma through STAT3 activation." (PMID 23667456, 2013). "In hepatocellular carcinoma, all three types of IFNs are found to induce apoptosis by inhibiting β-catenin signaling pathway via a STAT3- and DKK1-dependent pathway." (PMID 23056571, 2012). "Phosphorylated STAT3 was found in human hepatocellular carcinoma tissue samples and was expressed in tumor cells and also in monocytes." (PMID 22136659, 2011). "The growth of HepG2 human hepatocellular carcinoma cells was promoted by IL-22 through the activation of STAT3, ERK1/2 and the induction of antiapoptotic proteins." (PMID 21625390, 2011). "STAT3 has been shown to be constitutively active in a growing number of diverse human cancer cell lines and tumor tissues, including hepatoma cells." (PMID 20507639, 2010). "Recently, increased STAT3 activity was found in hepatocellular carcinoma and multiple myeloma in which there was silencing of SOCS-1 (suppressor of cytokine signalling-1) by gene promoter hypermethylation." (PMID 15354212, 2004). "This study, utilizing bioinformatics and experimental validation, has demonstrated that STA may exert its anti-hepatocellular carcinoma effects through multiple targets and pathways, particularly by regulating STAT3 and FN1." (PMID 40772037, 2025).
hepatocellular carcinoma (continued). "Additionally, STAT3 signaling, crucial for tumor malignancy, was markedly activated in hepatoma cells exposed to N‐CM, minimally impacted by sorafenib treatment." (PMID 39932456, 2025). "On one hand, H2S has been shown to promote proliferation, inhibit apoptosis, and enhance angiogenesis and migration of PLC/PRF/5 hepatoma cells via activation of the NF-κB or signal transducer and activator of transcription 3 (STAT3)-cyclooxygenase−2 (COX−2) signalling pathways." (PMID 41277458, 2025). "In this paper, we demonstrated that TTI-101, a small-molecule STAT3 inhibitor currently under investigation in a three-arm, Phase II trial for treatment of hepatocellular carcinoma, markedly reduced adenoma numbers in the AOM-DSS mouse model of CRC and was well tolerated." (PMID 41226842, 2025). "Similarly, IL-6/STAT3 pathway activation drives M1/M2 macrophage polarization, accelerating hepatocellular carcinoma progression." (PMID 40420174, 2025). "Moreover, STAT3 is involved in the development and progression of hepatocellular carcinoma (HCC) and colorectal cancer (CRC)." (PMID 40979569, 2025). "It was also demonstrated that PTPRD could regulate PD-L1 via its effects on STAT3 in human hepatocellular carcinoma, and consequently, enhanced STAT3 activity may support tumor immune evasion." (PMID 39985075, 2025). "Functionally, STAT3 is a key oncogenic transcription factor involved in promoting cell proliferation, survival, and immune evasion in hepatocellular carcinoma (HCC), while CASP3 plays a central role in executing apoptosis—a process often suppressed during cancer progression." (PMID 40599803, 2025). "Furthermore, overexpression of miR-10a-5p reduced phosphorylated STAT3 levels, whereas miR-10a-5p knockdown increased phosphorylated STAT3 in hepatoma cells, consistent with in vitro results." (PMID 41551164, 2025). "Clinically, safe and effective agents that inhibit STAT3 activation may offer avenues for hepatocellular carcinoma prevention and treatment." (PMID 40387965, 2025). "Moreover, FAT10 limits the efficacy of anti-VEGF therapy for hepatocellular carcinoma by simultaneously stabilising multiple proteins, including HIF1α, β-catenin, STAT3, and TAB3 proteins." (PMID 40374601, 2025). "Molecular docking simulations of various BSCA components with JAK2 and STAT3 proteins indicated specific components with higher binding affinities, suggesting their potential to induce apoptosis in hepatocellular carcinoma cells by modulating the JAK2/STAT3 pathway." (PMID 39940837, 2025). "In addition, consistent with our results, Bifidobacterium pseudolongum-generated acetate reached the liver via the portal vein, where it suppressed the IL-6/JAK1/STAT3 signaling pathway in hepatocytes, thereby preventing hepatocellular carcinoma." (PMID 40693815, 2025). "Accordingly, STAT3 inhibition in hepatoma cells mitigated the neutrophil‐conditioned medium's suppressive effects on sorafenib efficacy, highlighting a STAT3‐dependent mechanism through which neutrophil‐released soluble factors inhibit sorafenib's therapeutic efficacy." (PMID 39932456, 2025). "AKR1C3 participates in NF-κB signaling and IL6/STAT3 pathway, resulting in cell proliferation and metastasis in hepatocellular carcinoma (HCC) cells, while treatment with the AKR1C3 inhibitors could suppress tumor growth and promote cell death." (PMID 40603306, 2025). "B7-H3 promotes EMT in hepatocellular carcinoma through the Jak2/Stat3/Slug signaling pathway." (PMID 40519928, 2025). "In conclusion, SS-d effectively controls the proliferation of hepatocellular carcinoma cells by inhibiting the p-STAT3/C/EBPβ signaling pathway and reducing the expression of COX-2, thereby reinforcing its potential application in the treatment of hepatocellular carcinoma." (PMID 41011202, 2025). "In addition, dysregulated methylation or STAT3 activation is also associated with DDR2 expression in gastric cancer, epithelial ovarian cancer, and hepatocellular carcinoma." (PMID 39766183, 2024).
hepatocellular carcinoma (continued). "Prior research has underscored the pivotal role of Stat3 signaling activation in diverse liver physiological and pathological processes, encompassing liver regeneration, chronic liver inflammation, liver fibrosis, and hepatocellular carcinoma." (PMID 38440978, 2024). "A recent study demonstrated that increased STAT3 phosphorylation could lead to the upregulation of DRP1 expression in hepatocellular carcinoma." (PMID 39262325, 2024). "Furthermore, previous studies indicated that IL6 can activate Stat3 to modulate the promoter activity of FGL1 in hepatocellular carcinoma (HCC)." (PMID 39085849, 2024). "In the pre-metastatic microenvironment of hepatocellular carcinoma, the expression of CXCL12 can downregulate the transcription factor Paired Related Homeobox 1 (Prrx1), thereby inducing an increase in the protein and mRNA expression of CXCR4 in hepatocellular carcinoma cells via the STAT3 pathway." (PMID 38920657, 2024). "Furthermore, STAT3 promotes the transcription of Nanog in the tumor-initiating cells of CD24-positive hepatocellular carcinoma (HCC)." (PMID 38881902, 2024). "Research has shown that STAT3 inhibits the expression of downstream genes by upregulating miRNA expression, which contributes to the occurrence and development of diseases, such as hepatocellular carcinoma (HCC) and ischemic retina." (PMID 38172648, 2024). "ILC3s are generally seen as pro-tumorigenic, as suggested by studies in both hepatocellular carcinoma and colorectal cancer, in part due to their ability to induce tumor cell signal transducer and activator of transcription 3 (STAT3) activation and cellular proliferation." (PMID 38339226, 2024). "Moreover, in hepatocellular carcinoma cells, overexpression of STAT3 significantly reduced the expression of cell adhesion molecules but enhanced the expression of N-cadherin and Vimentin." (PMID 39195486, 2024). "Furthermore, B7-H3 promotes EMT in glioma and hepatoma cells through JAK2/STAT3/Slug pathway activation." (PMID 38468228, 2024). "SCH4 could promote tumor proliferation and metastasis by activating STAT3 signaling in hepatocellular carcinoma." (PMID 39834541, 2024). "Likewise, lack of SOCS2 regulates the inflammation and tumorigenesis mediated by STAT3 in hepatocellular carcinoma." (PMID 38245798, 2024). "Inflammatory mediators, whose activators or targets are transcriptional factors such as Signal Transducer and Activator of Transcription 3 (STAT3), and Nuclear Factor kappa B (NF-κB) play a vital role in the development of carcinogenesis hepatocellular carcinoma (HCC)." (PMID 39409068, 2024). "NCAPG2 was recently reported to directly bind with STAT3 to promote hepatocellular carcinoma." (PMID 38166947, 2024). "Moreover, PTPRO dephosphorylated JAK2 and downregulated JAK2/STAT3 signaling in hepatocellular carcinoma." (PMID 38182570, 2024). "NCAPG2 overexpression also promotes hepatocellular carcinoma and malignant melanoma metastasis and proliferation through activating the NF-kB and STAT3 signaling pathways and suppress apoptosis by activating the STAT3 signaling pathway." (PMID 37501987, 2023). "In addition, we also looked at the levels of p-EGFR, EGFR, p-STAT3, and total STAT3 protein expression, which are important signaling pathways involved in liver fibrosis and hepatocellular carcinoma." (PMID 37789318, 2023). "We speculate that metformin affects hepatocellular carcinoma cells sensitivity to sorafenib through the ATF4/STAT3 molecular pathway." (PMID 37326750, 2023).
hepatocellular carcinoma (continued). "RAF1 exerts dual roles in STAT3 activation; in hepatocellular carcinoma, RAF1 acts as a cell-autonomous tumor suppressor by negatively regulating STAT3 activation, while it has been described as a STAT3 activator in squamous cell carcinoma through its interaction with ROKα." (PMID 37020037, 2023). "STAT3-HIF1α-DHHC7 loop is a therapeutic target of hepatic carcinoma cells." (PMID 38051779, 2023). "For example, miR-375 inhibited progression of hepatocellular carcinoma by targeting JAK2/STAT3 signalling pathway; miR-375 reduced the stemness of gastric cancer cells through triggering ferroptosis; miR-375 also functioned as a tumour suppressor in tongue squamous cell carcinoma." (PMID 36476264, 2023). "In addition, riboophorin II (RPN2) induces the expression of MMP-9 through the STAT3 and NF-kB pathways, thereby promoting hepatocellular carcinoma metastasis." (PMID 36950520, 2023). "Therefore, the aim of this study was to investigate the promotion of ferroptosis and sorafenib sensitivity by metformin via ATF4/STAT3 in hepatocellular carcinoma cells." (PMID 37326750, 2023). "Our study clarified that curcumin could downregulate the expressions of HIF-1α/STAT3/VEGF signal transduction pathway in hepatocellular carcinoma, thus suppressing the proliferation and growth of the cancer cells." (PMID 37333486, 2023). "Notably, lenvatinib acts on radiation-induced Src/STAT3/NF-κB signal transduction to enhance the antitumor effect of radiation on hepatocellular carcinoma." (PMID 36495367, 2023). "Mitochondrial respiratory defects might enhance hepatoma cell invasiveness via the ROS-mediated signal transducer and activator of transcription 3 (STAT3)-NFE2L1-STX12-EMT axis." (PMID 37525297, 2023). "Interestingly, there are some shreds of evidence about how the cross-taking of DDR1 and STAT3 contributes to the development of hepatocellular carcinoma." (PMID 37271822, 2023). "A study using hepatocellular carcinoma (HCC) cells was carried out to determine if what myricetin causes autophagy and cell cycle arrest in HCC cells by modulating the MARCH1-regulated p38 MAPK/Stat3 signalling pathway." (PMID 37298616, 2023). "In both human hepatoma cell line HepG2 and in the mouse liver, Yang and colleagues found that the rmIL-22 could strongly activate STAT3 signaling, depending on the STAT3-binding tyrosine residues in IL-22R1." (PMID 37525285, 2023). "In addition, silibinin synergistically improves the response to sorafenib by hepatocellular carcinoma (HCC) cells by blocking STAT3." (PMID 36902166, 2023). "On the other hand, the decrease in serum IL-10 suggested that WCP against hepatocellular carcinoma might occur through an IL-10-regulated signaling pathway, so we examined its downstream STAT3 and p-STAT3 proteins." (PMID 37110586, 2023). "High levels of p-STAT3 have been reported, especially in hepatocellular carcinoma." (PMID 37762016, 2023). "Among the hubs, SORBS3 could co-activate ERα signaling to repress STAT3 signaling in hepatocellular carcinoma; however, the potential activation of ERα in luminal B BC requires further analysis." (PMID 37483500, 2023). "Likewise, in hepatocellular carcinoma, CAFs recruit normal DCs and induce their differentiation into regulatory DCs(RDCs) and dysfunctional DCs by activating the IL-6-mediated STAT3 pathway." (PMID 36759842, 2023). "In hepatocellular carcinoma, STAT3 acts on HOXD-AS1 promoter and activates HOXD-AS1 transcription." (PMID 36295083, 2022). "Given the role of STAT proteins in contributing to cell survival, oncogenic activation of these factors, especially STAT-3, has been found in diverse types of tumors including hepatocellular carcinoma, colorectal cancer, breast cancer, bladder cancer and hematological malignancies." (PMID 35203723, 2022). "STAT3 promotes cell growth in neurocytes, hepatocellular carcinoma cells, and colon cancer cells." (PMID 35810312, 2022).